DNPH1 (2'-deoxynucleoside 5'-phosphate N-hydrolase 1)
Description:
Part of a nucleotide salvage pathway that eliminates epigenetically modified 5-hydroxymethyl-dCMP (hmdCMP) in a two-step process entailing deamination to cytotoxic 5-hydroxymethyl-dUMP (hmdUMP), followed by its hydrolysis into 5-hydroxymethyluracil (hmU) and 2-deoxy-D-ribose 5-phosphate (deoxyribosephosphate). Catalyzes the second step in that pathway, the hydrolysis of the N-glycosidic bond in hmdUMP, degrading this cytotoxic nucleotide to avoid its genomic integration.
Synonyms: C6orf108; RCL; dJ330M21.3
Tractability: Small molecule: a structure with a bound ligand is known; a high-quality ligand is known. PROTAC: ubiquitination databases record sites on it; its protein half-life has been measured; a small molecule that binds it is known.
Target class: Enzyme; Hydrolase
Gene: Protein-coding gene on chromosome 6 (43,225,629 to 43,229,484, reverse strand). Ensembl gene ENSG00000112667.
Subcellular location: Cytoplasm; Nucleus
Subcellular location (Human Protein Atlas): Nucleoplasm; Cytosol
Pathways (Reactome):
Metabolism: Purine catabolism
Gene Ontology:
Molecular function: 5-hydroxymethyl-dUMP N-hydrolase activity; identical protein binding; protein binding; hydrolase activity, hydrolyzing N-glycosyl compounds; protein homodimerization activity
Biological process: deoxyribonucleoside monophosphate catabolic process; epithelial cell differentiation; nucleoside salvage; positive regulation of cell growth; purine nucleotide catabolic process; allantoin metabolic process; carbohydrate derivative metabolic process; dGMP catabolic process; nucleoside metabolic process
Cellular component: cytoplasm; cytosol; extracellular exosome; nucleus
Genetic constraint (gnomAD): Loss-of-function variants: 18 observed, 12.19 expected, observed/expected ratio (o/e) 1.48, 90% interval 1 to 1.91. The upper end of that interval is the gene's LOEUF score, 1.91, which puts it in group 6 of 6, group 1 being the genes least tolerant of losing a copy. Missense variants: 262 observed, 214.53 expected, observed/expected ratio (o/e) 1.22, 90% interval 1.1 to 1.35. Synonymous variants: 114 observed, 91.54 expected, observed/expected ratio (o/e) 1.25, 90% interval 1.07 to 1.46.
Homologues: Orthologues: chimpanzee DNPH1 (99% identical), macaque DNPH1 (94% identical), rabbit DNPH1 (83% identical), pig DNPH1 (78% identical), dog DNPH1 (75% identical), rat Dnph1 (71% identical), guinea pig DNPH1 (70% identical), mouse Dnph1 (70% identical), zebrafish dnph1 (49% identical).
Diseases named in the same sentence as DNPH1 in open-access papers:
DNPH1 is named in the same sentence as 13 diseases in open-access papers, as found by Europe PMC text mining. Sharing a sentence is not in itself a finding about the gene and the disease. The quoted sentences say what the papers report.
breast carcinoma (4 papers, 2022 to 2025). "Decreased levels of CASP8, DDX58, CPNE1, ULK3, PARK7, and BTN2A1, as well as increased levels of TNFRSF9, TNXB, DNPH1, and TLR1, were linked to an elevated risk of breast cancer." (PMID 39351539, 2024). "The cis-regions around DNPH1 and LRRC37A2 showed the strongest concordance between lead variants for protein levels and breast cancer risk." (PMID 37996402, 2023). "To summarise, the MR analysis showed that genetic elevation of CD160, DNPH1, LAYN, LRRC37A2 and TLR1 associated with breast cancer risk, and with similar effects on ER+ and ER− cancers." (PMID 37996402, 2023). "Of those, we present five proteins (CD160, DNPH1, LAYN, LRRC37A2 and TLR1) that show a potential causal role in breast cancer risk with confirmatory results in independent cohorts." (PMID 37996402, 2023). "In conclusion, by applying an MR approach to a broad range of circulating proteins we found that genetically elevated CD160, DNPH1, LAYN, LRRC37A2 and TLR1 were associated with breast cancer." (PMID 37996402, 2023). "We found that genetically lower levels of CD160 and LRRC37A2 and genetically higher levels of DNPH1, LAYN and TLR1 were associated with increased risk of breast cancer." (PMID 37996402, 2023). "Genetically increased circulating protein levels of DNPH1 were in our study associated with increased breast cancer risk, which is concordant with experimental studies suggesting that DNPH1 inhibition in breast cancer may be a promising avenue for drug development." (PMID 37996402, 2023).
schizophrenia (2 papers, 2024 to 2025). A major psychotic disorder characterized by abnormalities in the perception or expression of reality. "DNPH1 is highly expressed in the cerebral cortex and is one of the genes significantly associated with schizophrenia and brain structure features." (PMID 38637810, 2024). "Based on this, three-step SMR and colocalization analyses identified ITIH3 and CCS as being related to the risk of developing depression, while CTSS and DNPH1 are related to the onset of schizophrenia." (PMID 38637810, 2024). "Through coloc analysis, ITIH3 was conclusively associated with the onset of depression, CCS exhibited associations with depression at both the gene and protein levels, and CTSS and DNPH1 were implicated in the onset of schizophrenia at both the gene and protein levels." (PMID 38637810, 2024). "Furthermore, DNPH1, which is involved in axonal transport and brain structure, may be associated with the development of schizophrenia." (PMID 38637810, 2024). "A total of three such sites were identified: CCS for depression and CTSS and DNPH1 for schizophrenia." (PMID 38637810, 2024). "This suggests a potential role of DNPH1 in schizophrenia and its potential as a therapeutic target." (PMID 38637810, 2024).
cancer (6 papers, 2013 to 2025). A tumor composed of atypical neoplastic, often pleomorphic cells that invade other tissues. "Human nucleotide glycosidase DNPH1 represents an important drug target that, in combination with PARPi’s, offers a new avenue for treatment of BRCA-deficient cancers." (PMID 37884503, 2023). "The crystal structure of rat DNPH1, a potential target for anti-cancer therapies, suggested that various analogues of AMP can inhibit this enzyme." (PMID 35057823, 2022). "Some cancer cell lines are killed by cytokinins at low micromolar concentrations, a concentration range that inhibits the activity of DNPH1." (PMID 24260472, 2013). "DNPH1 is a potential target for anti-cancer therapies as it is involved in cellular proliferation and is up-regulated in several types of cancer." (PMID 24260472, 2013). "Recently, the crystal structure of rat DNPH1, a potential target for anti-cancer therapies, suggested that various analogs of AMP may inhibit this enzyme." (PMID 24260472, 2013). "More recently, high-resolution crystal structures revealed how DNPH1 can accommodate distinct nucleotides such as the N6-cyclopentyl AMP and the triciribine 5’-monophosphate used in anti-cancer therapies." (PMID 24260472, 2013).
psychiatric disorder (1 paper, 2024). A disorder characterized by behavioral and/or psychological abnormalities, often accompanied by physical symptoms. "Specific research on the connection between DNPH1 and psychiatric disorders is limited." (PMID 38637810, 2024).
tumour (1 paper, 2024). "Many downregulated genes in tumour‐infiltrating peripheral CD8+ T cells are associated with classical IFN responses (IFI6, IFI27, MX1, STAT1, EPSTI1 PARP9, ISG15), cell proliferation (STMN1, CENPF, HELLS, NUSAP1, and DNPH1), and T cell costimulation (CD28, TMIGD2, TNFRSF4, CD27, and TNFRSF18)." (PMID 39350478, 2024).
DNPH1 also shares sentences with these, for which no sentence is quoted: Alzheimer disease (1 paper); bipolar disorder (1); breast tumour (1); depression (1); Huntington disease (1); infection (1); melanoma (1); meningioma (1).